CYP2A6 (cytochrome P450 family 2 subfamily A member 6)
Diseases named in the same sentence as CYP2A6 in open-access papers (continued):
Sharing a sentence is not in itself a finding about the gene and the disease.
tumor (26 papers, 2011 to 2026). "In a separate cohort, the expression of CYP2A6 was also closely associated with tumor grades and favorable prognosis." (PMID 36818443, 2023). "CYP2A6 was also associated with worse clinicopathological characteristics including advanced tumor staging, vascular invasion, major portal vein invasion, intrahepatic metastasis, and increased AFP level in our study." (PMID 30148168, 2018). "In univariate analysis, the CYP2A6 genotype was significantly associated with tumour response rates; 66.7% for W/W patients vs 58.3% for W/V other than *1/*4 vs 32.3% for V/V or *1/*4 (Pearson χ2-test, P=0.019; trend test, P=0.008)." (PMID 21364592, 2011). "In multivariate logistic regression analysis, the CYP2A6 genotype was significantly associated with the tumour response after adjustment for ECOG performance status and sex." (PMID 21364592, 2011). "In HCC, reduced expression of CYP2A6 modulates the anti-tumor immunity by disrupting the equilibrium between 20-HETE and EETs." (PMID 36818443, 2023). "We detected the expression of CYP2A6 in tumor tissues and normal liver tissues, with the expression of CYP2A6 in normal liver tissues significantly enhanced compared to tumor tissues, consistent with the IHC staining data from the HPA database." (PMID 33455085, 2021). "Several studies hint at a previously unappreciated aspect of CYP2A6 in tumor, but current understanding of CYP2A6 function in tumor is controversial." (PMID 33455085, 2021). "Considered above, we assumed that downregulation of CYP2A6 and CYP2C8 in tumor tissues is associated with worse clinicopathological characteristics in HCC patients." (PMID 30148168, 2018). "HCC patients with CYP2A6 and CYP2C8 low levels in tumor tissues suffered from poorer overall survival (OS) compared to those with high CYP2A6 and CYP2C8 in GSE14520 profile (log ranks P = 0.01 and P = 0.006, respectively)." (PMID 30148168, 2018). "CYP2A6 expression is elevated in CA, AA tumor, and all BRCA tissue compared to normal breast tissue." (PMID 28684774, 2017). "We investigated the effect of the presence or absence of normal germline CYP2A6 on tumor mutational burden (TMB)." (PMID 41272073, 2025). "Not only that, TSIIA could increase CYP2A6 mRNA and protein levels in both normal liver tissue and tumor tissue." (PMID 33455085, 2021). "This provides a reasonable explanation for CYP2A6 intervention in tumor progression." (PMID 33455085, 2021). "Because cytochrome P450 2A6 (CYP2A6) mediates nicotine oxidation and the metabolic activation of tobacco-related procarcinogens, the involvement in tumor development of polymorphic CYP2A6 with impaired activities resulting from whole-gene deletion of CYP2A6 was postulated." (PMID 34193316, 2021). "In GSE14520 dataset, we identified the fact that low expressions of four CYPs including CYP2A6, CYP2C8, CYP2E1, and CYP4A11 in tumor tissues were significantly associated with worse OS in HCC patients (log ranks P = 0.01, 0.006, 0.024, and 0.007, respectively)." (PMID 30148168, 2018). "Additionally, HCC patients with low CYP2A6 and CYP2C8 levels in tumor tissues had higher risk of vascular invasion, major portal vein invasion, and intrahepatic metastasis (all P < 0.05)." (PMID 30148168, 2018). "And, low expression of CYP2A6 in tumor tissues contributed to worse survivals from HCC cases." (PMID 30148168, 2018). "Additionally, lower CYP2A6 and CYP2C8 are associated with advanced clinicopathological features including tumor staging, vascular invasion, intrahepatic metastasis, and high alpha fetoprotein (all P < 0.05)." (PMID 30148168, 2018). "When CYP2A6 is reduced in HCC, macrophage polarization is affected, creating a tumor microenvironment conducive to tumor growth." (PMID 39195558, 2024). "The expression of CYP2A6 and CYP2C9 were relatively lower in tumor tissues, while the expression of G6PD in HCC tumors was higher in tumor tissues than in normal tissues." (PMID 37051536, 2023).
tumor (continued). "Our results indicate that the expression level of CYP2A6 is reduced in HCC, which affects the polarization of macrophages, and creates a tumor microenvironment conducive to tumorigenesis." (PMID 33455085, 2021). "In our study, we found that several CYPs including CYP1A2, CYP2A6, CYP2C8, CYP2C9, CYP2E1, CYP3A4, and CYP4A11 were all downregulated in tumor tissues in HCC patients." (PMID 30148168, 2018). "Seven CYP450 genes including CYP1A2, CYP2A6, CYP2C8, CYP2C9, CYP2E1, CYP3A4, and CYP4A11 were downregulated in tumor tissues, which were validated in both GSE14520 and GSE36376." (PMID 30148168, 2018). "We report that the CYP genes with highest expression, ranked by the mean expression in tumor tissues for all patients, are: CYP1B1 (mean normalized expression 112.8), CYP4Z1 (92.2), CYP2A6 (75.7), CYP4X1 (65.1), CYP4B1 (31.5), CYP2A7 (30.8), and CYP4F8 (11.6)." (PMID 28684774, 2017). "Altogether, 224 overexpressed genes were identified in the tumor samples derived from the patients without PCR; among these, the gene sets associated with xenobiotic metabolism (e.g., CYP3A4, CYP2A6) exhibited significant enrichment." (PMID 38256136, 2024). "Immunofluorescence of tumor tissues also showed that TSIIA could improve the infiltration and expression of CYP2A6 in tumor tissues." (PMID 33455085, 2021). "Downregulation of CYP2A6 and CYP2C8 in tumor tissues links to poorer OS and RFS in HCC patients." (PMID 30148168, 2018). "Interestingly, in GSE36376 database, HCC patients with low CYP2A6 and CYP2C8 levels in tumor tissues suffered from more advanced edmondson grade and AJCC staging (all P < 0.05)." (PMID 30148168, 2018). "CYP2A6 activity has been has been correlated with lower bioactivation, which would lead to lower levels of NNK-related DNA adducts and a potential decrease in tumor induction." (PMID 28542511, 2017). "The direct interaction between Cyt c and CETP, CLEC11A, CYP2A6 and CYP2A7 has not been clearly revealed, but they have potential indirect associations in cholesterol metabolism, mitochondrial function, oxidative stress regulation and tumor microenvironment regulation." (PMID 40860340, 2025). "Conversely, hepatic periportal markers (e.g., ALDOB, HAL, ASS1) and a subset of CYP-related proteins (e.g., CYP2A6, CYP2A7, CYP2B6) were either absent or downregulated in the tumor region." (PMID 39567475, 2024). "Concentrations of Gamitrinib that trigger tumor cell killing (IC50 ~1-4 μM) do not affect cytochrome P450 isoforms CYP1A2, CYP2A6, CYP2B6, CYP2C8 or ion channel conductance (Nav1.5, Kv4.3/KChIP2, Cav1.2, Kv1.5, KCNQ1/mink, HCN4, Kir2)." (PMID 35129069, 2022). "They found that CYP2A6 protein was very heterogeneous in tumor cells and HCC do not uniformly overexpress the CYP2A6 protein, suggesting that increased expression of CYP2A6 occurred in a distinct subpopulation of neoplastic cells." (PMID 30148168, 2018).
blood cancers (1 paper, 2020). "Intriguingly, CYP2A6 deletion associated with increased blood cancer only in smokers (OR = 2.05, 95%CI: 1.19~3.53, p = 0.01, after adjustment)." (PMID 32131765, 2020).
digestive system cancer (1 paper, 2023). A primary or metastatic malignant neoplasm involving any part of the digestive system. "The results showed that the focus genes for target and digestive system cancers were ACE, PTGS2, CYP2C19, and CYP2A6, while the number of intersections with neurological diseases was 73, and the three shared a focus on ACE, PTGS2 and CYP2C19 (top left)." (PMID 37701374, 2023).
CYP2A6 also shares sentences with these, for which no sentence is quoted: adenocarcinoma (3 papers); fibrosis (2); kidney disease (2); leukopenia (2); liver fibrosis (2); anaemia (1); Anxiety (1); arteriosclerosis obliterans (1); autoimmune conditions (1); biliary tract cancer (1); cardiovascular diseases (1); Dependence (1); Diarrhoea (1); esophageal squamous cell carcinoma (1); Familial adenomatous polyposis (1); heart failure (1); Hyperammonemia (1); Hyperbilirubinemia (1); Hypoglycemia (1); lung squamous cell carcinoma (1); malaria (1); melanoma (1); multiple sclerosis (1); neurological diseases (1); oesophageal cancer (1); oral squamous cell carcinoma (1); pharyngeal cancers (1); Plasmodium falciparum malaria (1); rectal cancer (1); stomach diseases (1).
A further 4 diseases each share a sentence with CYP2A6 in 1 paper.